CNPY3 (canopy FGF signaling regulator 3)
Description:
Toll-like receptor (TLR)-specific co-chaperone for HSP90B1. Required for proper TLR folding, except that of TLR3, and hence controls TLR exit from the endoplasmic reticulum. Consequently, required for both innate and adaptive immune responses (By similarity).
Synonyms: ERDA5; PRAT4A; TNRC5; CAG4A; DEE60; EIEE60
Tractability: Antibody: UniProt predicts a signal peptide or a membrane-spanning region; the Human Protein Atlas places it where antibodies can reach. PROTAC: ubiquitination databases record sites on it; its protein half-life has been measured.
Gene: Protein-coding gene on chromosome 6 (42,929,115 to 42,939,903, forward strand). Ensembl gene ENSG00000137161.
Subcellular location: Endoplasmic reticulum
Subcellular location (Human Protein Atlas): Endoplasmic reticulum; Plasma membrane
Pathways (Reactome):
Immune System: Trafficking and processing of endosomal TLR
Gene Ontology:
Molecular function: protein binding; signaling receptor binding
Cellular component: endoplasmic reticulum lumen; endoplasmic reticulum
Genetic constraint (gnomAD): Loss-of-function variants: 19 observed, 31.61 expected, observed/expected ratio (o/e) 0.6, 90% interval 0.42 to 0.88. The upper end of that interval is the gene's LOEUF score, 0.88, which puts it in group 3 of 6, group 1 being the genes least tolerant of losing a copy. Missense variants: 299 observed, 338.11 expected, observed/expected ratio (o/e) 0.88, 90% interval 0.8 to 0.97. Synonymous variants: 138 observed, 142.34 expected, observed/expected ratio (o/e) 0.97, 90% interval 0.84 to 1.12.
Homologues: Orthologues: chimpanzee CNPY3 (99% identical), macaque CNPY3 (98% identical), pig CNPY3 (94% identical), dog CNPY3 (92% identical), rabbit CNPY3 (92% identical), rat Cnpy3 (88% identical), mouse Cnpy3 (88% identical), guinea pig CNPY3 (87% identical), zebrafish cnpy3 (55% identical), tropical clawed frog cnpy3 (53% identical), Drosophila melanogaster CNPYb (36% identical), Caenorhabditis elegans C11H1.7 (24% identical). Paralogues in human: CNPY4 (38% identical).
Diseases named in the same sentence as CNPY3 in open-access papers:
CNPY3 is named in the same sentence as 20 diseases in open-access papers, as found by Europe PMC text mining. Sharing a sentence is not in itself a finding about the gene and the disease. The quoted sentences say what the papers report.
prostate carcinoma (3 papers, 2025). A carcinoma that arises from epithelial cells of the prostate gland. "For instance, CNPY3 has been implicated in prostate cancer, where it serves as a direct target for gambogic acid to induce pyroptosis by altering its lysine lactylation and promoting lysosomal rupture." (PMID 40055606, 2025). "Notably, high CNPY3 expression has been observed in several malignancies, including gastric and prostate cancers, where it is associated with aggressive tumor characteristics and poor prognosis." (PMID 40055606, 2025). "SIRT1 can eliminate Kla of CNPY3, promoting lysosomal rupture and triggering specific pyroptosis in prostate cancer cells." (PMID 39897556, 2025). "In addition, SIRT1 delactylated canopy FGF signaling regulator 3 (CNPY3) and caused CNPY3 mislocalization, leading to lysosomal rupture, CatB release, caspase-1/GSDMD activation, and pyroptosis in prostate cancer cells." (PMID 41008630, 2025). "This inhibits lactylation at the K215 and K224 sites of CNPY3 and promotes the lysosome-dependent CatB/caspase 1/GSDMD pyroptotic pathway, inducing pyroptosis in DU145 cells and suppressing prostate cancer progression." (PMID 39897556, 2025).
gastric cancer (2 papers, 2025). A primary or metastatic malignant neoplasm involving the stomach. "In gastric cancer, CNPY3 enhances liver metastasis by forming a regulatory axis with SLITRK4, which drives endocytosis and recycling of the TrkB receptor, ultimately fostering metastatic potential." (PMID 40055606, 2025). "Additionally, we found that the most common cancer types with increased CNPY3 and GRP94 were breast, colon, and gastric cancers." (PMID 41296387, 2025).
asthma (1 paper, 2015). "This pilot study implies a positive association between CNPY3, ERAS, FOSL1 and aspirin-intolerant asthma, suggesting that these findings would be useful for further investigations of NSAIDs mechanism." (PMID 26646719, 2015).
breast carcinoma (1 paper, 2025). "To further investigate the role of CNPY3 in breast cancer progression and metastasis, we next silenced CNPY3 in human breast cancer cell lines MCF-7 (ER+PR+BC) and MDA-MB-231 (TNBC) using a CRISPR/Cas9 lentiviral system." (PMID 41296387, 2025). "Further studies comparing CNPY3 dependency across a broader panel of breast cancer subtypes will be a focus of our ongoing research." (PMID 41296387, 2025). "In this study, we aimed to investigate the role of CNPY3 in human breast cancer progression and metastasis." (PMID 41296387, 2025). "In this study, we demonstrated that expression levels of CNPY3 and GRP94 were elevated in human breast cancers, and a high level of CNPY3 was associated with an aggressive phenotype and poor clinical outcome." (PMID 41296387, 2025). "Higher expression of CNPY3 correlated with cancer progression and poor clinical outcomes in breast cancers." (PMID 41296387, 2025). "In a large group of breast cancer patients (n = 1907), patients with high levels of CNPY3 and HSP90B1 expression had shorten overall survival and progression-free survival." (PMID 41296387, 2025). "For the first time, our study uncovers the vital role of CNPY3 in the progression and metastasis of breast cancer, suggesting that CNPY3 may be a novel biomarker and therapeutic target for cancers." (PMID 41296387, 2025). "We found that deletion of CNPY3 in human breast cancer cells significantly decreased tumor growth and prolonged survival and reduced metastasis, suggesting that CNPY3 may be a potential therapeutic target for cancers." (PMID 41296387, 2025). "For the first time, our study uncovers the critical roles of CNPY3 in the progression and metastasis of breast cancer, suggesting that CNPY3 may be a novel biomarker and therapeutic target for cancers." (PMID 41296387, 2025). "We silenced CNPY3 in human breast cancer cells using a CRISPR/Cas9 system." (PMID 41296387, 2025). "Targeting CNPY3 in human breast cancer cells reduced tumor growth and metastasis." (PMID 41296387, 2025). "Furthermore, targeting CNPY3 in human breast cancer cells by CRISPR/Cas9 significantly reduced tumor growth and metastasis in vitro and in vivo." (PMID 41296387, 2025). "Both CNPY3 and GRP94 overexpression were correlated with TNBC, advanced stage, high NPI, and poorly differentiated breast cancers." (PMID 41296387, 2025). "Both CNPY3 and HSP90B1 were overexpressed in breast cancers." (PMID 41296387, 2025). "We found that CNPY3 and GRP94 were elevated in human breast cancers compared to normal tissue." (PMID 41296387, 2025). "Additionally, both CNPY3 and GRP94 had consistent prognostic value for overall survival and progression-free survival in breast cancer." (PMID 41296387, 2025).
colon adenocarcinoma (1 paper, 2025). "More recent studies showed that CNPY3 was upregulated in colon adenocarcinoma, and a higher level of CNPY3 was correlated with worse clinical outcomes." (PMID 41296387, 2025). "Furthermore, CNPY3 is upregulated in colon adenocarcinoma, where its expression correlates with poor clinical outcomes and promotes tumor cell proliferation and migration in vitro." (PMID 41296387, 2025).
colon cancer (1 paper, 2025). "Building on the established role of CNPY3 in various cancers, our study underscores its significance in colon cancer, drawing parallels to findings in other malignancies." (PMID 40055606, 2025).
diffuse brain atrophy (1 paper, 2021). "To date, three individuals with biallelic CNPY3 variants have been reported, and their MRI showed diffuse brain atrophy and hippocampal malrotation." (PMID 34858471, 2021).
proteinopathies (1 paper, 2025). "In agreement with our bioinformatics analyses and our experimental validation of CNPY3 APA in cell models of TDP-43 depletion, we observed significant CNPY3 APA, corresponding with increased expression of CNPY3 isoform variant 2 in the frontal cortex of TDP-43 proteinopathy patients." (PMID 40454469, 2025).
triple-negative breast carcinoma (1 paper, 2025). An invasive breast carcinoma which is negative for expression of estrogen receptor (ER), progesterone receptor (PR), and human epidermal growth factor receptor 2 (HER2). "Furthermore, high expression of CNPY3 and HSP90B1 correlated with poor differentiation, PR negative status, triple-negative breast cancer (TNBC), a high Nottingham Prognostic Index (NPI), and an aggressive basal subtype." (PMID 41296387, 2025).
cancer (3 papers, 2025). A tumor composed of atypical neoplastic, often pleomorphic cells that invade other tissues. "While CNPY3 has been implicated in cancer progression, its influence on the tumor stroma remains less understood." (PMID 40055606, 2025). "CNPY3 depletion also modulated fibroblast behavior, inhibiting their transformation into cancer-associated fibroblasts." (PMID 40055606, 2025). "Further study is needed to understand how CNPY3 regulates the tumor microenvironment and anti-tumor immunity for the development of combination therapies for cancers." (PMID 41296387, 2025). "Our study demonstrated that CNPY3, a cochaperone of immune chaperone GRP94, was elevated in the majority of human cancers, and the overexpression of CNPY3 and GRP94 predicts an aggressive phenotype and poor clinical outcome." (PMID 41296387, 2025). "Previous studies have identified CNPY3 as an important regulator in various cancers, exhibiting multifaceted roles in cancer progression and response to treatment." (PMID 40055606, 2025). "Despite these limitations, our study simultaneously investigates the role of CNPY3 in both tumor biology and the cancer microenvironment." (PMID 40055606, 2025). "This study suggests that CNPY3 is a potential biomarker and novel therapeutic target for cancers." (PMID 41296387, 2025). "By promoting fibroblast migration and CAF transformation, CNPY3 may contribute to a dynamic and supportive tumor stroma that accelerates cancer progression." (PMID 40055606, 2025). "Notably, CAFs play a key role in remodeling the tumor microenvironment by secreting factors that support cancer progression, making it essential to investigate whether CNPY3 regulates fibroblast behavior and contributes to CAF activation." (PMID 40055606, 2025). "However, the role of CNPY3 in human cancers is still not fully understood." (PMID 41296387, 2025). "We used genomic and clinical information from multiple databases to profile CNPY3 and GRP94 in human cancers." (PMID 41296387, 2025). "We first investigated the CNPY3 and GRP94 expressions in 20 human cancers by the Human Protein Atlas." (PMID 41296387, 2025). "Consistent with CNPY3, GRP94 was highly expressed in cancer and metastasis tissues compared with ANT (right)." (PMID 41296387, 2025). "Other anti‐inflammatory factors, including canopy FGF signaling regulator 3 (CNPY3) and the NOD‐like receptor family pyrin domain containing 3–caspase‐1–ASC complexes, have been shown to induce pyroptosis as an antitumor mechanism in cancers." (PMID 40900810, 2025). "CNPY3 and GRP94 were overexpressed in most human cancers compared with normal tissue." (PMID 41296387, 2025). "For the first time, we found that CNPY3 was significantly overexpressed in cancer and metastatic tissues but not in ANT (left)." (PMID 41296387, 2025). "However, the role of CNPY3 in cancer development and progression is still not completely understood." (PMID 41296387, 2025). "However, the role of CNPY3 in cancer development and progression is still not fully understood." (PMID 41296387, 2025).
tumor (3 papers, 2025 to 2026). "However, the underlying mechanism of CNPY3 in regulating the tumor microenvironment and anti-tumor immunity needs to be further investigated." (PMID 41296387, 2025). "Canopy FGF signaling regulator 3 (CNPY3) has been implicated in tumor progression." (PMID 40055606, 2025). "In vivo studies demonstrated that CNPY3 knockdown resulted in smaller tumor sizes and weights than controls." (PMID 40055606, 2025). "We found that silencing of CNPY3 causes significantly compromised MCF-7 and MDA-MB-231 tumor cell growth compared with control tumor cells." (PMID 41296387, 2025). "For the first time, we found that deletion of CNPY3 significantly reduced tumor growth and metastasis in vitro and in vivo." (PMID 41296387, 2025). "By elucidating the roles of CNPY3 in CC and its microenvironment, our findings pave the way for the development of novel therapeutic strategies targeting both tumor cells and CAFs, ultimately enhancing treatment efficacy." (PMID 40055606, 2025). "Third, while our study identifies CNPY3’s involvement in several tumor-related pathways, the precise molecular mechanisms remain to be fully elucidated." (PMID 40055606, 2025). "Elevated CNPY3 levels were correlated with advanced tumor stages, older patient age, and poor prognosis." (PMID 40055606, 2025). "Secretion levels of fibroblast growth factors, including EGFR, VEGF, TGFB1, and PDGF-BB, were decreased in the medium of CNPY3-knockdown cells, indicating a potential paracrine effect of CNPY3 on the tumor stroma." (PMID 40055606, 2025). "Functional assays indicate that CNPY3 enhances tumorigenic properties, including cell proliferation and migration, while also influencing the tumor microenvironment and fibroblast behaviors." (PMID 40055606, 2025). "Our study delved into the role of CNPY3 in modulating the tumor microenvironment, particularly focusing on its effects on fibroblast behaviors." (PMID 40055606, 2025). "Collectively, these findings suggest that CNPY3 plays a critical role in promoting CC progression and modulating the tumor microenvironment, potentially serving as a prognostic biomarker and therapeutic target." (PMID 40055606, 2025). "CNPY3 is a crucial regulator in CC progression, correlating with tumor aggressiveness and poor patient outcomes." (PMID 40055606, 2025). "Tumors in the KD + PBS group were significantly smaller than those in the KD-Con + PBS group, suggesting that CNPY3 knockdown significantly affects tumor growth in vivo." (PMID 40055606, 2025). "By elucidating the molecular pathways through which CNPY3 impacts tumor and stromal cell interactions, this research aims to provide a foundation for new therapeutic approaches that disrupt supportive microenvironment interactions in CC." (PMID 40055606, 2025). "In addition, CNPY3 knockdown significantly reduced tumor growth in the KD + 5-FU group compared to other groups, with the smallest tumor volumes observed in this group, demonstrating enhanced sensitivity to 5-FU following CNPY3 knockdown." (PMID 40055606, 2025). "In addition, the changes in the UPR pathway and immune-related genes in the tumor microenvironment were significantly dependent on alterations in CNPY3 and GRP94." (PMID 41296387, 2025). "Increased CNPY3 expression correlated with advanced tumor stages and poorer prognosis." (PMID 40055606, 2025). "Additionally, in macrophages within the tumor microenvironment, CNPY3 is essential for TLR2 trafficking, playing a crucial role in preventing phospholipid peroxidation-induced resistance to ferroptosis." (PMID 40055606, 2025). "Knockdown of CNPY3 in colon tumor cell lines decreased tumor cell growth and migration in vitro." (PMID 41296387, 2025). "In vivo experiments also confirmed that CNPY3 knockdown significantly reduced tumor growth in mice." (PMID 40055606, 2025).
tumor (continued). "Functionally, CNPY3 drives CRC cell proliferation, invasion, and tumor growth via a cholesterol synthesis-independent oncogenic program." (PMID 42212339, 2026). "We confirmed that CNPY3 was completely knocked out in both MCF-7 and MDA-MB-231 tumor cells from different passages." (PMID 41296387, 2025). "Mechanistically, we found that GRP94 and its co-chaperone CNPY3 regulate UPR pathway genes and immune-related genes in the tumor microenvironment." (PMID 41296387, 2025). "However, it is unclear whether its co-chaperone, CNPY3, plays a critical role in tumor progression." (PMID 41296387, 2025). "Intriguingly, targeting CNPY3 in human ER+PR+ and TNBC cells by CRISPR/Cas9 significantly decreased tumor growth, prolonged survival, and reduced metastasis in vitro and in vivo." (PMID 41296387, 2025). "In vitro and in vivo experiments further validated that CNPY3 knockdown enhanced CC cell sensitivity to 5-fluorouracil, as evidenced by reduced IC50 values in cell viability assays and enhanced tumor growth suppression in 5-FU-treated xenograft models." (PMID 40055606, 2025). "Our study suggested that CNPY3, a co-chaperone of GRP94, may play important roles in regulating the tumor microenvironment and anti-tumor immune response." (PMID 41296387, 2025). "However, how the CNPY3-UPR signaling pathway regulates the tumor microenvironment is still not clear." (PMID 41296387, 2025).
infection (1 paper, 2021). The state of being infected such as from the introduction of a foreign agent such as serum, vaccine, antigenic substance or organism. "In young adult lung, there was increased expression of Tlr9, Cnpy3, and Ctsb at day 3 post H1N1 or H3N2 infection." (PMID 34829979, 2021).
CNPY3 also shares sentences with these, for which no sentence is quoted: autoimmune thyroid disease (1 paper); Breast Tumor (1); colorectal cancer (1); diffuse large B-cell lymphoma (1); graft versus host disease (1); metastatic cancers (1); ovarian carcinoma (1); tuberculosis (1).